TNF (tumor necrosis factor)
Diseases named in the same sentence as TNF in open-access papers (continued):
Sharing a sentence is not in itself a finding about the gene and the disease.
tumor (continued). "Regarding the risk for malignancies, studies in mice attributed an important role to TNF in the process of tumor immune surveillance." (PMID 29751683, 2018). "We further confirmed the effect of PV on TNFα-mediated cell apoptosis in xenograft tumor tissues using TUNEL staining." (PMID 29506556, 2018). "A proliferation-inducing ligand (APRIL), a member of the tumor necrosis factor (TNF) superfamily, is a newly discovered target of miR-383, contributing to tumor apoptosis." (PMID 29951542, 2018). "One of the functions of the regulatory T-cells is suppressing immune responses in vivo and in vitro directly or via the production of pro-inflammatory cytokines such as IL-10 and TNF which promotes tumor cell growth." (PMID 29849947, 2018). "This was accompanied by the production of IFN-γ, interleukin-β (IL-1β) and TNF-α inhibiting tumor growth." (PMID 29466981, 2018). "In line, recent CAC studies in mice demonstrate that enriching high-fat diets with TNF- and IL-6-inhibiting supplements leads to the reduction of inflammation and mucosal injury in the colons of mice and ultimately to less tumor development." (PMID 30591653, 2018). "Pro-inflammatory cytokines, such as TNF-α, IL-1β, and IL-6, contribute to the induction of tumor development by enhancing cancer stemness." (PMID 30486830, 2018). "This process leads to phagocytosis of the targeted tumor cells and cell death by pro-apoptotic cytokines such as IL-2, IL-12, and TNF-α." (PMID 30103457, 2018). "It highlighted the involvement of bioactive sphingolipids ceramide and its impact to facilitate the host immune surveillance, restricting tumor growth through pro-inflammatory cytokine TNFα generation." (PMID 30701020, 2018). "Increased TNFα in the tumor microenvironment tips the balance towards invasion leading to decreased overall survival and disease-free survival." (PMID 30018735, 2018). "Recently, TNF/iNOS-producing DCs (TIP-DCs), a novel type of inf-DCs that produce TNF-α and nitric oxide (NO) was shown to be critical for tumor growth control upon treatment with adaptive CD8 T cell transfer." (PMID 30619378, 2018). "In MC-38 tumor models, we demonstrated that TgMGLL stimulated the expression of proinflammatory cytokines (IL-1β and TNFα) and reduced the levels of anti-inflammatory cytokines (IL-10, Arg-1, and TGFβ) in a CB2-dependent manner in TAMs." (PMID 29968710, 2018). "Firstly, we profiled the transcript levels of major tumor microenvironment cytokines IL-6, IL-10, tumor necrosis factor-α (TNF-α), and transforming growth factor-β (TGF-β) in PC3 cells in both conditions: with ectopically expressed AIRE and AIRE knockdown." (PMID 29795364, 2018). "A decrease in the expression of ADAM-17 by silencing FoxM1 led to an inhibition of cell proliferation, tumor growth, and the production of tumor necrosis factor α." (PMID 29776401, 2018). "This deleterious effect of TNF was further supported in TNF knockout mice that display reduced tumor growth." (PMID 29593717, 2018). "For example, non-tumor cell-derived TNF-α, IL-6, IL-8, and IL-1β stimulate tumor cell proliferation, invasion, and metastasis via paracrine signaling." (PMID 30038719, 2018). "High levels of TNF-α lead to tumor cell necrosis and apoptosis, and mediate immune cytotoxicity and production of inflammatory cytokines." (PMID 29896191, 2018). "Decreased levels of TG have been connected with increased circulating levels of IL-6, TNF-α which are thought to induced the tumor cell proliferation and inhibit apoptosis." (PMID 30400953, 2018). "Abundant expression of MHC class II can also lead to potent tumor-specific CD4 T cell responses that dampen cytotoxic CD8 T cell responses in a TNF-related manner." (PMID 29032503, 2018). "Hemorrhagic necrosis of tumors is observed in a rapid manner subsequent to TNF-alpha and melphalan administration, with disruption of cell–cell adhesive junctions occurring within minutes, followed by tumor vascular collapse 24 h later." (PMID 30170620, 2018).
tumor (continued). "Tumor promotion can also be induced by tumor necrosis factor-α (TNF-α) and TNF-α-inducing protein (Tipα) of Helicobacter pylori stimulates progression phase." (PMID 29570697, 2018). "In tumors, the membrane form of TNF-alpha on tumor cells interacts mainly with TNF-R2 to activate clearance of pro-tumor suppressor cells via the production of reactive oxygen intermediates with signaling through ceramide." (PMID 30170620, 2018). "TAM2 treated with DSF/Cu and Rego showed up-regulation of the antitumor TNF-α and down-regulation of the pro-tumor TGF-β1, demonstrating the re-polarization of the phenotype towards M1." (PMID 29732051, 2018). "TC1 primary tumour cells had higher levels of several immunostimulatory factors (IFNγ, IL-2, TNFα), including antigen presenting molecules (H2-K1) as compared to the A9 metastatic tumour cells." (PMID 29440650, 2018). "Matrix metalloproteinase 9 (MMP9) plays a key role in tumor cell migration and invasion induced by various tumor-promoting cytokines and growth factors, including TNF-α and EGF33." (PMID 30042418, 2018). "TNF-α and IL-1 are some of the earliest and most potent systemic mediators of inflammation known to stimulate tumor cell adhesion, invasion and neoangiogenesis and potentiate metastasis formation." (PMID 29728948, 2018). "Here, we initially observed elevated levels of pro-inflammatory cytokines (most notably TNF), infiltration of inflammatory cells, and upregulation of four GPCR-associated genes (CCR10, P2RY8, ARRB1, and RGS10) in human HCC tumor and paracancerous specimens." (PMID 29445190, 2018). "Adipocytes are known to play a significant role in promoting tumor progression by secreting cytokines including IL-6, IL-1, IL-8, and TNF-α." (PMID 30134951, 2018). "Tumor cells highly expressing TNFR2 resist TNF-induced cell death via binding of the ligand to the TNFR2." (PMID 29892300, 2018). "T cells stimulated with either MACS or EasySep_MoDCs loaded with tumor antigens showed a slight increase in TNF-α expression, compared with unstimulated T cells." (PMID 29434528, 2018). "TGFβi significantly increased IFNγ secretion against all tumor targets tested, and significantly increased TNFα secretion against all tumor targets except CHLA-255." (PMID 30400618, 2018). "NF-κB plays a pivotal role in linking chronic inflammation to cancer development through its ability to upregulate several inflammatory and tumor promoting cytokines such as IL-6, IL-1α, and TNF-α, as well as survival genes such as BCL2 and BCLXL." (PMID 29772687, 2018). "In a mouse model of skin carcinogenesis where loss of TNF-α suppresses tumour formation, transplantation of B-cells from TNF-α competent mice is sufficient to restore tumour formation." (PMID 29725601, 2018). "(i) The pro-inflammatory cytokines IL-2, TNF, and IFNγ are important for a good T-cell response against the tumor." (PMID 29346301, 2018). "Other studies have documented the ability of Salmonella enterica to suppress tumor growth inducing inflammasome, by activation of interleukin-1β (IL-1β) and TNF-α." (PMID 30302344, 2018). "We have verified that spontaneous cell fusion between tumor and endothelial cells is enhanced by inflammatory factors such as TNF-α." (PMID 29581976, 2018). "In a tumor microenvironment, it has the anti-tumor phenotype, which is characterized with the expression of TNF-α, IL-1, and IL-12." (PMID 30405034, 2018). "A host of factors associated with lymphangiogenesis and tumor progression were upregulated following treatment with docetaxel, including VEGFC, TNF-α, IL1, among others." (PMID 29976154, 2018). "Long-term screening for rare neoplasms is important as part of the safety monitoring for any pediatric rheumatology patient receiving anti-TNF therapy." (PMID 29540190, 2018). "Upon TNF stimulation, we observed a general increase in the apoptosis rate of shRev-erbα-, shTNF- and shBmal1-HD-MY-Z cells, corroborating a tumour suppressing role for TNF." (PMID 30065253, 2018).
tumor (continued). "Among several identified factors secreted by tumors, vascular endothelial growth factor A (VEGFA), placental growth factor, transforming growth factor β (TGF-β), and tumor necrosis factor (TNF) were first demonstrated to prepare “soil” for tumor cells." (PMID 30061895, 2018). "TNF, on the other hand, mediates inflammation and can promote the growth of a tumor by assisting in angiogenesis, epithelial to mesenchymal transition, and other mechanisms." (PMID 29696001, 2018). "Antitumoral responses were mainly characterized by the secretion of tumor necrosis factor-alpha (TNFα) and granulocyte macrophage-colony stimulating factor (GM-CSF) when stimulated with autologous tumor." (PMID 30042343, 2018). "Combination of CAR-T cells with an OV armed with IL-2 and TNF-a was able to control both the primary tumor and tumor metastasis." (PMID 30405639, 2018). "These neutrophils were able to secrete TNFα, which in combination with IFNγ, exerted synergistic cytotoxic effects on endothelial and tumor cells within the tumor microenvironment." (PMID 29765907, 2018). "TNF-α was predominantly produced by tumor cells, suggesting the participation of both cell types in the secretion of inflammatory cytokines into the culture medium." (PMID 30094378, 2018). "Cytokines, such as tumor necrosis factor (TNF), interleukin (IL)-1, and IL-6, are secreted from tumor cells and induce exposure of TF and release of microparticles in endothelial cells." (PMID 30180930, 2018). "Increased expression and secretion of TNF-α by glial cells promote tumor growth by amplifying inflammation and neoangiogenesis." (PMID 30038719, 2018). "Contact-dependent mechanisms including perforin/granzyme and Fas-FasL, and contact-independent mechanisms such as production of TNFα or IFNγ – are utilized by CD8 T cells in tumor environments with varying degrees of preference." (PMID 29464051, 2018). "For this purpose, we challenged them with whole tumor cell antigens or with TNF-α plus LPS and compared the expression of HLA-DR and CD86." (PMID 29434528, 2018). "At the end of culture, functional assays demonstrated that these cells were potent and specific in their ability to kill tumor cells bearing target and secrete large quantities of interferon and tumor necrosis factor." (PMID 29368612, 2018). "TGFβ1 and TNFα are pleiotropic cytokines, which can have both tumor promoting and tumor suppressive effects depending on the context." (PMID 29682184, 2018). "Tumor necrosis factor (TNF) is widely accepted as a tumor-suppressive cytokine via its ubiquitous receptor TNF receptor 1 (TNFR1)." (PMID 29892300, 2018). "The inhibition of PI3K survival cascades has been shown to sensitize tumor cells to cytokines including TNF-α and tumor necrosis factor-related apoptosis-inducing ligand (TRAIL)." (PMID 29719632, 2018). "In summary, we report six pediatric rheumatology patients who developed neoplasms during or after treatment with anti-TNF agents." (PMID 29540190, 2018). "In all 4 cases, enhanced lymphocyte infiltration was observed when PBMC where incubated with tumor cell supernatant of cetuximab treated IFNγ/TNFα stimulated cancer cells." (PMID 30192802, 2018). "Accordingly, using a TGFβ receptor inhibitor SM16 led to a suppression of tumor growth by the anti-tumor N1-like TANs in mice, which expressed TNFα, MIP1α, H2O2, and NO, ultimately being cytotoxic to cancer cells." (PMID 30349530, 2018). "We have demonstrated for the first time that a Lf-bearing dendrimer-based gene delivery system complexed to a plasmid DNA encoding TNFα, TRAIL, or IL12 can lead to tumor suppression after intravenous administration." (PMID 29493296, 2018). "We further confirmed the effect of combined TNFα and ionomyin treatment on cell apoptosis in xenograft tumor tissues using TUNEL staining." (PMID 29506556, 2018). "Although a systemic increase in IFN-γ and TNF-α was observed, IL-10 expression increased in the tumor-bearing mice treated with metformin." (PMID 29899823, 2018).
tumor (continued). "Proinflammatory cytokines like IL6 and tumor necrosis factor α (TNFα) present in the tumor microenvironment further add to the ER stress induced UPR activation." (PMID 30159133, 2018). "In tumor cells, TNFα activates the NF-κB signaling to stimulate EMT induction, cell survival, proliferation, migration, and chemoresistance." (PMID 30356176, 2018). "Overproduction of TNF-α alters the adhesive ability of tumor cells and enhances their metastatic potential." (PMID 29467927, 2018). "M2-polarized CD11b+ cells promote tumor growth, invasion, metastasis, and angiogenesis through the release of growth and motility factors, including VEGFs, FGFs, tumor necrosis factor (TNF), platelet-derived growth factor (PDGF), and chemokines." (PMID 29766399, 2018). "Marigo and colleagues demonstrated that the CD40/CD40L axis is necessary for tumor rejection mediated by CD8+ T cells in the presence of tumor necrosis factor (TNF) derived from dendritic cells (DCs)." (PMID 29329591, 2018). "In line with this we found increased infiltration of PD-1+ T cells in the tumor microenvironment and reduced production of TNFα by CD4+ and CD8+ T cells in the lung of STAT1−/− mice bearing tumour." (PMID 30647851, 2018). "In a nude mice xenograft model, our data revealed that TNFα combined with ionomycin remarkably synergized the anti-tumor effect of TNFα." (PMID 29506556, 2018). "The clinical effect was associated with TNF-α-mediated extravasation of leukocytes, necrosis, hemorrhage and infiltration of cytotoxic CD8+ T cells into the tumor site." (PMID 29588627, 2018). "After the challenge of FV-experienced mice with FV-induced FBL-3 tumor cells (48 h), we also found an increased percentage of IFNγ and TNFα producing NK cells as well as a higher expression of FasL." (PMID 30292240, 2018). "Manipulation of PML is a key mechanism to regulate tumor-associated angiogenesis and IFN and TNF-mediated angiogenic suppression." (PMID 29416846, 2018). "IFN-γ and TNF-α are typically produced in the context of ongoing immune responses against infectious and tumor challenges." (PMID 29896191, 2018). "ROS activate NF-κB, TNF-α, and STAT3 signaling pathways in inflammatory cells and tumor cells to release TNF, NOX2, IL-6, IL-2, IL-8, and CXCL12 involved in the change of TME." (PMID 29770167, 2018). "Metastasis is promoted by activated macrophages in the tumor microenvironment releasing TNFα and thereby driving metastasis." (PMID 30591653, 2018). "Under inflammatory conditions, immune cells and tumor cells release various inflammatory mediators, including interleukin-1β, interleukin-6, and tumor necrosis factor (TNF), which can suppress albumin synthesis in liver cells." (PMID 29685957, 2018). "One North American study involving six pediatric centres (ours included) examined the time of neoplasm in JIA patients after anti-TNF therapy." (PMID 29540190, 2018). "TAMs induce EMT of tumor cells by secreting factors such as interleukelin-6 (IL-6), interleukelin-8 (IL-8), tumor necrosis factorα (TNFα), TGFβ, EGF, VEGF, matrix metalloproteinase-2 (MMP-2) and MMP-9." (PMID 30157906, 2018). "MACinflam produced in cultures containing IL-6 plus TNFα or IFNγ also mediated significant tumor cell lysis." (PMID 29632539, 2018). "TNF-α activates signaling pathways such as NF-κΒ, which correlates with TNF-α-mediated tumor cell invasion and migration." (PMID 29467927, 2018). "These transformed neoplastic cells consequently produce inflammatory mediators including TNFα and IL1β that form a closed paracrine loop to perpetuate this tumor-reactive microenvironment." (PMID 29594035, 2018). "In tumor models, neutrophils can be converted from anti-tumor phenotype (N1: release ROS and TNF-α) to pro-tumor phenotype (N2: increased Arginase, CCL2, and CCL5) by the TGF-β stimulation." (PMID 29776443, 2018).
tumor (continued). "In that study, they showed a dynamic cooperation between CD8+ T cells and myeloid cells in the microenvironment of regressing tumors and demonstrated killing of tumor cells by TAMs via TNF-α production and phagocytosis." (PMID 30469401, 2018). "The neoplasms at our centre developed late after drug exposure with a median of 5.0 years from anti-TNF onset." (PMID 29540190, 2018). "The secretion of IFNγ and TNFα by NK cells in response to tumor target stimulation (DAOY) following overnight treatment with IL-2 was measured in supernatants at Day 7, 14, and 1 week, 3 weeks, and 1 month (33 days) post-expansion." (PMID 30400618, 2018). "This was correlated with a higher production of pro-inflammatory TNF-α, IL-1β, and IL-6 cytokines and a stronger stimulatory effect on tumor growth achieved by these activated macrophages as compared with controls." (PMID 29435437, 2018). "Among M2 macrophages, tumor-associated macrophages (TAMs) stimulate regulatory T cell differentiation and secrete several factors (e.g., TGF-β, TNF-α and IL-10) to create a favorable environment for tumor growth and immunosuppression promotion." (PMID 29541395, 2018). "These receptors have been found to be elevated in tumors and in the plasma of cancer patients as a mechanism of tumor survival by counteracting the anti-cancer potential of TNF-alpha." (PMID 30170620, 2018). "It is generally indicated that TNF-α promotes progression of RCC by enhancing tumor invasion and epithelial-mesenchymal transition and that lower serum adiponectin levels and higher serum leptin levels are associated with higher aggressiveness of RCC20–23." (PMID 28986556, 2017). "Activated CD4+T-lymphocytes produce inflammatory cytokines such as, IFN-γ and TNF-α, that can both suppress tumor survival and upregulate the expression of MHC molecules on the surface of tumor cells." (PMID 28220118, 2017). "TNFα has previously been utilized in antitumor therapies because of its cytotoxic effects on tumor cells." (PMID 28199969, 2017). "The signaling axis of TNF-ROS-NF-κB induced by hypoxia in tumor cells has also been reported to lead to the production of various inflammatory cytokines." (PMID 29215599, 2017). "In vitro and in vivo studies have demonstrated strong anti-tumor activity of TNF-α in different types of cancers." (PMID 29278364, 2017). "Inducing apoptosis via the Fas–FasL or the TNF pathway is another mechanism by which NK cells are able to kill a target and has been described for various tumor cells as well as for pathogen infected cells." (PMID 29213274, 2017). "The evidence was the significantly elevated secretion of IFN-γ or TNF-α by tumor-specific immune cells of RdB/IL12/DCN-treated mice compared with RdB/IL-12-treated mice." (PMID 28002796, 2017). "TNFα, which is a pro-inflammatory cytokine, also promotes tumor development, neurovascularization and metastasis of tumors." (PMID 29246138, 2017). "In this study, we show that TNF-α preactivated-hMSCs exert a much stronger tumor-promoting effect than inactivated hMSCs via CCL5/β-catenin/Slug pathway in CRC development." (PMID 28542126, 2017). "On the one hand, STAT1/3 mediates TNFα-induced senescence by promoting expression of anti-proliferative, inflamma-tory, and tumor suppressor genes involved in main-taining the senescent state." (PMID 29176033, 2017). "TNF-α is a central proinflammatory cytokine contributing to malignant tumor progression in tumor microenvironment." (PMID 29238068, 2017). "Although TNF-α was shown to have toxic effects on tumor cells at high doses, it demonstrated a tumor-promoting role in pre-clinical studies." (PMID 28346397, 2017). "M1 macrophages have tumor-killing capacity and express a number of factors including iNOS, IL-1β, and TNF-α." (PMID 28415741, 2017). "Cancer cells produce various cytokines, such as tumor necrosis factor-α and interleukin-6, and this phenomena can increase the number of tumor-infiltrating neutrophils around a tumor." (PMID 28039452, 2017).